MMP8 (matrix metallopeptidase 8)
Diseases named in the same sentence as MMP8 in open-access papers (continued):
Sharing a sentence is not in itself a finding about the gene and the disease.
lung disease (11 papers, 2014 to 2025). "Second, MMP8 is highly sensitive to reactive oxygen species, which are often associated with lung disorders." (PMID 35059324, 2021). "An increasing body of evidence suggests that neutrophil extracellular traps (MMP-8 and calprotectin) in TB may cause tissue destruction and pulmonary dysfunction like other lung diseases." (PMID 35371847, 2022). "In summary, we have shown that adult and pediatric CF patients with moderate to severe CF lung disease exhibit increased serum levels of MMP-8, MMP-9, and YKL-40 and that this association occurs rather organ specific as is not influenced by the co-existence or absence of CFLD." (PMID 25545245, 2014). "Adults and children with moderate to severe CF lung disease exhibited significantly increased serum expression of MMP-8, MMP-9, YKL-40 and TIMP-1." (PMID 25545245, 2014). "In addition, neutrophils, one type of granulocytes, secrete serine proteases including neutrophil elastase, cathepsin G and proteinase-3, as well as MMP-8 and MMP-9, which may lead to destruction of the alveolar tissue and increase the risk of lung disease." (PMID 30400967, 2018). "MMP-8 is a critical mediator of lung parenchymal damage other lung diseases, such as COPD and ventilator-induced lung injury, and MMP-8 inhibition improves outcomes in a murine model of lung injury." (PMID 25996154, 2015). "Liver and pancreas represent two other organ systems that are, apart from the lung, frequently affected by CF and thus might act as potential confounders of the observed up-regulation of MMP-8, MMP-9, YKL-40 and TIMP-1 in CF lung disease." (PMID 25545245, 2014). "Hence, MMP-8, MMP-9, and YKL-40 might represent novel serological markers of CF lung disease and pulmonary exacerbations." (PMID 25545245, 2014). "However, an important patient group was not included in their MMP8 analyses: non-TB lung disease." (PMID 34403447, 2021). "Together, these data indicate that the observed increased expression of MMP-8, MMP-9, YKL-40, and TIMP-1 occur indeed relatively specific for the existence of CF lung disease without being affected by pancreas and liver disease as other major manifestations of CF." (PMID 25545245, 2014).
mucositis (11 papers, 2017 to 2026). Mucositis is inflammation and damage of the mucous membranes lining the mouth and other parts of the gastrointestinal (GI) tract. "According to the Authors, who showed increasing collagenase activity in implants with peri‐implantitis and mucositis compared to healthy implants, the assessment of MMP‐8 in PICF served as a reliable diagnostic test to differentiate between peri‐implant health and disease." (PMID 40101934, 2025). "Additionally, peri-implant treatment had a significantly higher impact on MMP-8 reduction in patients with PI than in those with peri-implant mucositis." (PMID 35329310, 2022). "In comparison to the Control and ALA groups, 5-FU treatment enhanced MMP-1, MMP-2, MMP-8, and TIMP-1 activation in sera and tissues in the Mucositis + ALA group." (PMID 36290656, 2022). "MMP-1, MMP-2, MMP-8, and TIMP-1 activities in serum, stomach, small intestine, and large intestine were significantly higher in the Mucositis group in comparison to the Control and ALA groups (p < 0.05–0.0001)." (PMID 36290656, 2022).
tuberculosis (11 papers, 2015 to 2025). A chronic, recurrent infection caused by the bacterium Mycobacterium tuberculosis. "In conclusion, we describe an association of plasma MMP-8 with sputum M. tuberculosis culture positivity at the beginning and after 6 months of tuberculosis treatment, in a cohort of patients of mixed HIV serostatus." (PMID 35510939, 2022). "Elevated plasma MMP-8 at tuberculosis diagnosis and after 6 months of tuberculosis treatment was associated with sputum culture positivity, indicating that plasma MMP-8 is a candidate biomarker for monitoring treatment response." (PMID 35510939, 2022). "Our group has previously demonstrated that elevated plasma MMP-8 is associated with lipoarabinomannan positivity and neutrophil count in HIV-associated tuberculosis." (PMID 35510939, 2022). "In patients without HIV infection, elevated sputum MMP-1, MMP-2, MMP-3, and MMP-8 concentrations decrease after just 2 weeks of tuberculosis treatment." (PMID 35510939, 2022). "Neutrophil-derived MMP-8 secretion is upregulated in Mtb infection and neutrophils from AMPK-deficient patients express lower levels of MMP-8, suggesting a key role for MMP-8 in tuberculosis immunopathology." (PMID 30404221, 2018). "This study is not the first to identify an association of MMP-8 with culture positivity in patients receiving tuberculosis treatment." (PMID 35510939, 2022). "In patients starting tuberculosis treatment and then receiving antiretroviral therapy for HIV who go on to develop paradoxical tuberculosis–immune reconstitution inflammatory syndrome (IRIS), plasma MMP-8 is also increased at tuberculosis diagnosis and at tuberculosis-IRIS presentation." (PMID 35510939, 2022). "Consequently, plasma MMP-8 is a potential biomarker to enhance tuberculosis treatment monitoring and screen for possible culture positivity." (PMID 35510939, 2022). "Together, these findings suggest that plasma MMP-8 may be a surrogate plasma marker of mycobacterial load and neutrophil-driven immune responses in tuberculosis." (PMID 35510939, 2022). "Indeed, they concluded that plasma analysis of MMP-1 and MMP-8 was a better discriminator for tuberculosis in men than in women." (PMID 27478294, 2016). "In HIV-associated TB, plasma matrix metalloproteinases (MMP), including MMP-8, and procollagen III N-terminal propeptide are associated with Mycobacterium tuberculosis bloodstream infection and 12-week mortality." (PMID 39219411, 2025). "They further found that hypoxia caused increased secretion of MMP-8, MMP-9, and NE in neutrophils, which in turn drives the destruction of major structural proteins of the lungs such as type I collagen, gelatin, and elastin, resulting in more severe tuberculosis tissue destruction." (PMID 34327245, 2021). "Although AMPK may play a protective role in tuberculosis, it has also been reported to exert an immunopathological effect by driving the secretion of neutrophil matrix metalloproteinase-8 (MMP-8), resulting in matrix destruction and cavitation, which enhance the spread of Mtb." (PMID 30404221, 2018). "In plasma, MMP-1, MMP-8, and procollagen III N-terminal propeptide (PIIINP), a matrix degradation product released during collagen turnover, are elevated in patients with tuberculosis compared with healthy or respiratory symptomatic controls." (PMID 35510939, 2022). "A study showed that all MMP-8, MMP-9, TIMP-1, IL-6, VEGF, and TGF-b1 are higher in exudates compared to transudates and that MMP-8 and IL-6 are significantly higher in tuberculosis patients than in cancer patients." (PMID 35326567, 2022). "In this longitudinal analysis of patients with tuberculosis receiving treatment, we found that concentrations of plasma MMP-1, MMP-8, MMP-10, and PIIINP decreased with effective tuberculosis treatment over 2 months." (PMID 35510939, 2022).
tuberculosis (continued). "More recently, some studies have reported the association between sputum conversion at 60 day of TB treatment with decreases in serum levels of CRP, CXCL10, IL-17, MMP-8, as well as with cytokine responses after M. tuberculosis-specific in vitro stimulation of peripheral blood." (PMID 27494953, 2016). "Sputum MMP-1 and MMP-8 are significantly elevated in patients with tuberculosis at diagnosis compared with controls, irrespective of HIV serostatus." (PMID 35510939, 2022).
type 2 diabetes (11 papers, 2015 to 2025). "In addition, recently it has been suggested that MMP-8 is associated with insulin receptor degradation, and high serum MMP-8 levels with an increased risk of diabetes mellitus type II." (PMID 28407807, 2017). "This study aims to evaluate the association between glycemic control, inflammatory markers (IL-1β, IL-6, MMP-8), and periodontal health in patients with type 1 and type 2 diabetes." (PMID 40283677, 2025). "For this purpose, the present study was conducted with the aim of comparing salivary MMP‐8 levels in patients suffering from chronic generalized periodontitis with type 2 diabetes." (PMID 38433295, 2024). "The impact of type 2 diabetes on levels of salivary MMP-8, MMP-9, RANKL, and OPG was also investigated." (PMID 26989414, 2016). "This study aimed to compare the activity of salivary matrix metalloproteinase‐8 (MMP‐8) in patients with moderate to severe generalized chronic generalized periodontitis between healthy individuals and those with type 2 diabetes who were referred to the Tabriz School of Dentistry." (PMID 38433295, 2024). "We tested the hypothesis that type 2 diabetes adversely influences the prevalence of the periodontal pathogens investigated and the levels of salivary MMP-8, MMP-9, RANKL, and OPG." (PMID 26989414, 2016). "There were evidences for the association of MMP9 with type 2 diabetes, but not the case for MMP8." (PMID 26252209, 2015). "In hypercholesterolemic patients with type 2 diabetes, elevated MMP-7 and MMP-8 concentrations were reduced by atorvastatin, along with their ratios to TIMP-1, through suppression of inflammatory mediators." (PMID 39200884, 2024). "Elevated aMMP-8 but not total MMP-8 levels in mouthrinse and saliva recently have been shown to predict the clinical manifestation of systemic inflammatory states such as type II diabetes." (PMID 37249720, 2024). "Our data show that type 2 diabetes has no significant influence on the prevalence of the investigated periodontal pathogens, or the levels of salivary MMP-8, MMP-9, and OPG." (PMID 26989414, 2016). "Moreover, we were unable to detect a significant difference in levels of salivary MMP-8, MMP-9, and OPG between individuals with and without type 2 diabetes." (PMID 26989414, 2016).
gastric cancer (10 papers, 2006 to 2024). A primary or metastatic malignant neoplasm involving the stomach. "A contrary outcome was seen when studying gastric cancer, where prognosis was worse in patients with low and with high MMP-8 levels when compared to patients with intermediate concentrations." (PMID 39917664, 2024). "Overexpression of HOXC-AS1 would accordingly sponge greater quantities of miR-99a-3p, leading to the upregulation of MMP8, eventually facilitating the progress of gastric cancer." (PMID 35884594, 2022). "In pancreatic and gastric cancer, Ephrin-B1 induces the secretion of MMP8 and is later cleaved by MMP8 as a feedback loop." (PMID 34059618, 2021). "The expression of MMP8 mRNA has been detected only in a few chondrosarcomas, hepatocellular carcinoma and gastric cancer samples." (PMID 31514474, 2019). "Because MMP-8+17C>G and MMP-8−381A>G were found to be in complete linkage disequilibrium, we decided to study the distribution of MMP-8–799C>T, MMP-8+17C>G in our group of gastric cancer patients." (PMID 16940985, 2006). "Conversely, in liver and gastric cancers, high levels of MMP8 worsen the prognosis." (PMID 31514474, 2019). "Similarly for gastric cancer, MMP8 level was higher in well-differentiated tumors, yet it did not affect patient survival." (PMID 31514474, 2019). "Interestingly, low or high MMP8 serum levels correlated with poor prognosis in gastric cancer patients." (PMID 31514474, 2019). "However, MMP8 activity can also be harmful, as shown for pancreatic and gastric cancers, in which the interaction between MMP8 and Ephrin-B1 seems crucial, and hepatocellular carcinoma, where MMP8 was shown to activate the PI3K/Akt/Rac1 pathway." (PMID 31514474, 2019). "The enzymatic activities of MMP2 and MMP3 increased (MMP2 rs2285053 CC: 888.60 vs. CT: 392.00, p <0.0001; MMP3 rs679620 AA: 131.10 vs. GG: 107.74, p=0.015), whereas those of MMP8 decreased (MMP8 rs1940475 TT: 133.78 vs. CC: 147.54, p=0.011) in gastric cancer tissues." (PMID 29285307, 2017). "To corroborate these observations, we now assessed MMP-2 and MMP-9 with new techniques in an expanded group of gastric cancer patients (n=81) and included for comparison MMP-7, MMP-8 and the tissue inhibitors of MMPs, TIMP-1 and -2." (PMID 16538217, 2006). "No MMP8 SNPs were correlated to nasopharyngeal carcinoma or gastric cancer and its clinicopathological features." (PMID 31514474, 2019). "The value of MMP-2 as an independent prognostic marker for gastric carcinomas is underscored by our observation that MMP-9, MMP-7, MMP-8, TIMP-1 and TIMP-2 have no prognostic relevance." (PMID 16538217, 2006).
rheumatoid arthritis (10 papers, 2012 to 2025). A chronic, systemic autoimmune disorder characterized by inflammation in the synovial membranes and articular surfaces. "In murine models, the deficiency of MMP8 increases the severity of rheumatoid arthritis, leading to a greater expression of IL-1β." (PMID 40299554, 2025). "In patients with rheumatoid arthritis, invasive tenosynovitis is associated with an increased rate of tendon rupture due to increased MMP-8 activity." (PMID 23981230, 2013). "Among them, MMP8 has been reported to be a NETs-associated autoantigen in rheumatoid arthritis (RA)." (PMID 36361646, 2022). "Despite treatment with NSAIDS and corticosteroids, similar GCF MMP-8 levels in patients with rheumatoid arthritis and healthy individuals were found which suggests that rheumatoid arthritis tends to overproduce this enzyme." (PMID 37342498, 2023). "However, MMP-8 is associated not only with PRD, but also with rheumatoid arthritis (RA), certain types of cancer, cancer progression, immune cell infiltration, connective tissue damage, smoking, obesity, and the regulation of the innate immune system." (PMID 41002709, 2025). "A notable aspect of this study was the impact of AG on MMPs, including MMP-1, MMP-3, MMP-8, and MMP-13, which are key targets in inflammatory arthritis, including OA and rheumatoid arthritis." (PMID 39125316, 2024). "Matrix metalloproteinases-3 (MMP-3), a member of the matrix metalloproteinases, can degrade extracellular proteoglycans and type IV collagen; activate the activities of MMP-1, MMP-8 and MMP-9; accelerate articular cartilage aging; and exacerbate osteoarthritis (OA) and rheumatoid arthritis (RA)." (PMID 38667174, 2024).
bronchiectasis (9 papers, 2008 to 2025). Segmental, irreversible dilation of the bronchial tree resulting in the accumulation of secretions which leads to obstruction. "MMP-8 is also expressed by bronchial epithelium and macrophages in patients with bronchiectasis." (PMID 24828408, 2014). "For example, Tayloret al. found that increased levels of MMP-9, as well as MMP-8 and increased MMP:TIMP ratios, correlated with decreased lung function and higher levels of inflammatory markers in patients with bronchiectasis." (PMID 40174958, 2025). "MMP-8 and MMP-9 are significantly increased in patients with bronchiectasis compared with healthy controls and significantly increased during bronchiectasis exacerbations." (PMID 40174958, 2025). "In patients with bronchiectasis, the presence of Rothia was found to be negatively correlated with pro-inflammatory factors such as IL-8, IL-1β, MMP-1, MMP-8, and MMP-9 in sputum." (PMID 38779669, 2024). "MMP-8 and MMP-9 levels were also significantly higher in patients with bronchiectasis than in healthy controls and were strongly correlated with the progression of bronchiectasis." (PMID 36902466, 2023). "In a cohort of adults with bronchiectasis, the abundance of Rothia species was negatively correlated with pro-inflammatory markers (interleukin (IL)-8 and IL-1β) and matrix metalloproteinase (MMP)-1, MMP-8 and MMP-9 in sputum." (PMID 36403054, 2022). "In the same study, whereas levels of MMP-8 and MMP-9 were increased in bronchiectasis, their primary inhibitor TIMP-1 was not, indicating a protease-antiprotease imbalance." (PMID 40174958, 2025).
colitis (9 papers, 2015 to 2024). Inflammation of the colon. "In a trinitrobenzene sulfonic acid (TNBS)-induced colitis rat model, the level of MMP8 is reported to be elevated about 3-fold in urine." (PMID 35274006, 2022). "As expected, mice with acute DSS-induced colitis had significantly increased expression of Mmp3, Mmp8 and Mmp9 compared to control mice." (PMID 28561062, 2017). "A group studying the Na+/H+ exchanger (NHE3) discovered that NHE3−/− mice developed spontaneous colitis restricted to the mucosa of the distal colon with a concomitant 15-fold increase in MMP-8 expression." (PMID 25948887, 2015). "Previous studies have demonstrated elevated MMP-8 in murine colitis and IBD36,37." (PMID 34183667, 2021). "In addition, increased Mmp8 expression was found in the groups with colitis." (PMID 38510236, 2024). "The expression of S100a9, S100a8, Lcn2, Il1f9, Mmp8, and Mmp9 were significantly increased in CD45+ cells from Il17b-/- colitis mice (P < 0.05)." (PMID 36814913, 2023). "Taken together, it suggested that neutrophil infiltration occurred during the course of DSS-induced colitis, while Tanshinone IIA significantly reduced neutrophil infiltration as evidenced by decreased expression of Ly6G and MMP-8, respectively." (PMID 26881040, 2016). "It was recently demonstrated that this is a novel mechanism for MMP induced neutrophil infiltration in IBD where MMP-8, -9, and PE were upregulated in the inflamed intestines of IBD patients and in mice with DSS induced colitis." (PMID 25948887, 2015). "Infiltrating macrophages were seen to be a major source of MMP-8, -9, and -10 in human IBD and a mouse model of colitis and isolated IgG plasma cells from IBD patients were shown to produce high and sustained amounts of MMP-3." (PMID 25948887, 2015).